RNU2-46P (RNA, U2 small nuclear 46, pseudogene)
Gene: Small nuclear RNA gene on chromosome 9 (95,859,904 to 95,860,016, forward strand). Ensembl gene ENSG00000252847.
Homologues: Orthologues: macaque U2 (89% identical), rabbit U2 (60% identical), rat LOC120101107 (58% identical), chimpanzee U2 (56% identical), rabbit U2 (56% identical), rabbit U2 (53% identical), rabbit U2 (52% identical), pig U2 (50% identical), rabbit U2 (49% identical), dog U2 (43% identical). Paralogues in human: U2 (70% identical), RNU2-4P (69% identical), RNU2-2 (68% identical), RNU2-6P (68% identical), RNU2-32P (67% identical), RNU2-59P (67% identical), RNU2-17P (66% identical), RNU2-33P (66% identical), RNU2-48P (66% identical), RNU2-68P (66% identical), RNU2-26P (65% identical), RNU2-3P (65% identical), and 65 more.